AFP (alpha fetoprotein)
Diseases named in the same sentence as AFP in open-access papers (continued):
Sharing a sentence is not in itself a finding about the gene and the disease.
Cirrhosis (continued). "In the present context of South Korea, men and women aged > 40 years who are at a high risk of developing liver cancer (cirrhosis or hepatitis B or C carriers) underwent abdominal ultrasound and AFP testing every 6 months as part of the national cancer screening program." (PMID 38138277, 2023). "The missing correlation of AFP with the LSM could thus be explained by a loss of functional liver tissue in cirrhosis." (PMID 36941982, 2023). "The link between viral etiology and elevated AFP may be due to the former’s association with cirrhosis." (PMID 36831565, 2023). "In addition, patients treated with DAAs were elderly patients with cirrhosis with high serum AFP levels, which are the main risk factors for HCC development." (PMID 36117166, 2022). "While more and more HCV-infected patients achieved sustained virologic response (SVR) and gained benefits from HCV eradication, the risk of HCC development persists, especially for those with HCC-related risk factors, such as diabetes, cirrhosis, and high alpha-fetoprotein (AFP)." (PMID 36366510, 2022). "Univariate analysis showed that risk score, main tumour size, cirrhosis, TNM staging, BCLC staging, CLIP staging and AFP were related to OS; while multinodular, cirrhosis, BCLC staging, CLIP staging and risk score were independent prognostic risk factors in multivariate analysis." (PMID 33962640, 2021). "The relative expression of UGT1A6 was notably associated with cirrhosis and serum AFP." (PMID 34337056, 2021). "In addition to PAR2, we found that serum AFP, cirrhosis, and advanced TNM stage were independent risk factors for recurrence and advanced TNM and histological grade were independent risk factors for OS." (PMID 34199695, 2021). "This showed that the AFP model could accurately distinguish Asian HCC patients with HBV-related cirrhosis with low recurrence risk and high recurrence risk, results similar to those seen in Italian patients." (PMID 32974380, 2020). "Tumor size, multinodular, cirrhosis, serum AFP level, and TNM stage were found to be positively associated with OS (P < 0.05 for all cases, Fisher's exact test), whereas sex and TNM stage were positively associated with cancer recurrence (P values < 0.05 for all cases, Fisher's exact test)." (PMID 32596342, 2020). "Second, detailed laboratory data allowed us to differentiate the risk of HCC incidence, showing that age > 70, male sex, cirrhosis, treatment-experienced, serum albumin < 3.5 g/dL at pw12, and AFP > 7 ng/mL at pw12 were significantly associated with the development of HCC." (PMID 32933027, 2020). "Our study found that in a population of patients with HCV-cirrhosis, every increase of 100 ng/ml in AFP levels was associated with a 1% increase in the hazard of death and contributes to the literature with information concerning this specific subgroup of patients with HCC." (PMID 33134370, 2020). "AFP is the standard diagnostic tool for cirrhosis associated liver cancer." (PMID 32854238, 2020). "Stratification analyses indicated that the lower circRNA-5692 expression was significantly associated with abnormal higher levels of AFP (P = 0.001), cirrhosis history (P = 0.001), larger tumor size (P = 0.042), and distant metastasis (P = 0.025), but not other measures tested in this population." (PMID 31776329, 2019). "AASLD guidelines suggest that adding AFP to ultrasound may improve detection of HCC in at-risk patients with cirrhosis." (PMID 30675135, 2019). "The incidence of outfield progression was not significantly correlated with any of the studied factors (e.g. total number of lesions, gender, subcapsular location of the lesion, cause of the cirrhosis, Child-Pugh score, T2-weighted or diffusion-weighted signal intensity, or AFP level at baseline)." (PMID 28441447, 2017). "Higher AFP level may be associated with more severe cirrhosis, more frequent vascular invasion, higher tumor burden, and poorer prognosis." (PMID 28103953, 2017).
Cirrhosis (continued). "It is well known that persistently elevated AFP levels are related to the presence of HCC and that its determination can be helpful for a better definition of at-risk patients (i.e., patients with a history of cirrhosis); hence, AFP is the most widely tested biomarker in HCC." (PMID 22792474, 2012). "AFP levels obtained from serum proteins, cfDNA, and CTCs showed no strong association with tumor stage, multicentricity, tumor size, the presence of lymphovascular invasion, cirrhosis, or ascites, except for CTCs, which exhibited higher counts in patients with ascites." (PMID 41002319, 2025). "However, diagnostic CT/MRI may be warranted in some patient subgroups with higher PLC risk, such as those with Child-Pugh B cirrhosis, clinically significant portal hypertension, or elevated AFP levels." (PMID 36881615, 2023). "The risk of PLC in these patients supports short-interval ultrasound as a reasonable recall recommendation, although diagnostic CT/MRI imaging may be warranted in some subgroups with higher PLC risk, such as patients with more advanced cirrhosis or those with elevated AFP levels." (PMID 36881615, 2023). "This is because AFP is not distinctive and specific for cancer diagnosis: serum AFP may not demonstrate elevated levels in approximately 30-40% of HCC patients, and AFP fluctuations are seen not only in HCC but also in chronic liver diseases caused by cirrhosis or chronic viral hepatitis." (PMID 36686731, 2022). "The mRNA expression of ACE2 was related to some clinical parameters – age, AFP level and cirrhosis – of the HCC patients, it was also found to be associated with the prognoses of HCC patients, where the potential clinical value of ACE2 expression could be seen." (PMID 34369278, 2021). "Cirrhosis was associated with age (p = 0.0026), BMI values (p = 0.0274), albumin levels (p < 0.0001), platelet counts (p < 0.0001), prothrombin times (p < 0.0001), hyaluronic acid levels (p < 0.0001), AFP levels (p < 0.0001), and the presence of HCC (p = 0.0017)." (PMID 25713769, 2015). "Exacerbation of infectious hepatitis or cirrhosis may also cause a transiently elevated AFP level." (PMID 22559879, 2012). "Thus, for those patients with lower AFP levels (first risk group), the AFP might be increasing because of the effects of inflammation/cirrhosis are higher than therapeutic effect in the early follow-up period." (PMID 23216929, 2012). "Model description: The multivariable logistic regression model was constructed using variables clinically associated with recurrence risk, including MTM subtype, age, cirrhosis, MVI, AFP, and PIVKA-II." (PMID 41598441, 2026). "After adjustment for age, cirrhosis, microvascular invasion, AFP, and PIVKA-II, MTM subtype remained an independent predictor of early recurrence with borderline statistical significance (adjusted OR = 3.47, 95% CI = 0.88–13.59, p = 0.075)." (PMID 41598441, 2026). "The diagnostic efficacy of these plasma markers in distinguishing HCC from healthy individuals, as well as from patients with hepatitis B or cirrhosis, appears to be slightly superior to that of AFP." (PMID 41474641, 2026). "Current professional recommendations for HCC surveillance, including the Thailand HCC guideline, suggest screening using ultrasound (US) coupled with serum alpha-fetoprotein (AFP) every 6 months in patients with cirrhosis." (PMID 41490253, 2026). "In patients with cirrhosis, comparable diagnostic sensitivity for HCC were observed between AFP-L3 and AFP in two American and one European prospective phase 3 studies." (PMID 40269686, 2025). "AFP levels also increase in other liver diseases like hepatitis C, non-alcoholic fatty liver, and cirrhosis." (PMID 40365190, 2025). "These patients were predominantly male and had cirrhosis, lower platelet levels (<200,000 103/mL), reduced albumin levels, and elevated alpha-fetoprotein (AFP) levels." (PMID 41379183, 2025).
Cirrhosis (continued). "In a large-scale multicenter study (n = 1284), serum DKK1 levels were significantly elevated in patients with HCC compared to those with cirrhosis or chronic HBV infection, which displayed complementary diagnostic potential with AFP." (PMID 40269686, 2025). "For example, in a study involving 40 HCC patients with liver cirrhosis, the combiROC analysis of miR-199a with miR-21-5p resulted in a lower AUC for differentiating HCC from cirrhosis compared to the combined AUC of AFP and miR-21-5p." (PMID 40141205, 2025). "Society guidelines recommend semi-annual abdominal ultrasound plus serum alpha-fetoprotein (AFP) for patients with cirrhosis and those with chronic hepatitis B viral (HBV) infection." (PMID 41375033, 2025). "Among these, the statherin-derived peptide DSSEEKFLR demonstrated outstanding discrimination between HCC and cirrhosis (AUC = 0.968), outperforming AFP (AUC = 0.648)." (PMID 41474787, 2025). "XE23CI also developed cirrhosis, and following a raised alpha-fetoprotein (AFP), was diagnosed with HCC." (PMID 40684071, 2025). "Previously, we showed that serosal invasion was an independent predictor of OS time on a par with the preoperative AFP level, hepatic cirrhosis, and the presence of invasion of the hepatic veins." (PMID 40046521, 2025). "The sensitivity of 18F-PSMA-1007 PET/CT was not correlated with those clinical and pathological features, such as cirrhosis, AFP levels, tumor number, MVI, or histologic grade." (PMID 41438989, 2025). "With these cut‐off values, cirrhosis status was accepted as the outcome feature, and when univariate LR analysis was performed, the highest OR value AFP was obtained (COR = 9.11 (CI: 6.62–12.51), p < 0.001)." (PMID 40384539, 2025). "Current HCC screening guidelines primarily recommend AFP testing and ultrasound (US) for high-risk patients with chronic HBV infection and/or cirrhosis." (PMID 40269686, 2025). "Regarding the similarity to HBV-HCC or HCV-HCC patients, HBCV-HCC patients had characteristics that were more similar to those of HCV-HCC patients, including smaller tumor size, higher cirrhosis rate, and lower AFP." (PMID 39743539, 2025). "The HCC Early detection Screening (HES) algorithm enhanced AFP surveillance for HCC by incorporating age, Alanine aminotransferase (ALT), platelet count, AFP rate of change, and cirrhosis etiology." (PMID 41294748, 2025). "By identifying key indicators such as the prevalence of cirrhosis, elevated AFP levels, and specific MRI characteristics like arterial phase hyperenhancement and portal venous washout, clinicians can achieve more accurate and timely diagnoses." (PMID 39857748, 2025). "We found that 6-monthly routine HCC surveillance with US would be cost-effective but that health and economic outcomes varied with differing adherence, cirrhosis diagnosis age, surveillance intervals, and the use of AFP." (PMID 40584144, 2025). "In cirrhosis caused by HCV, risk factors for the development of HCC have been reported to include zinc deficiency, high AFP levels, low BTR, and male gender." (PMID 40109879, 2025). "Compared with the non-GT 3 group, patients with GT 3 were with younger age, lower PLT, higher AFP, higher FIB-4, higher APRI scores, increased risk of baseline cirrhosis and HCV reoccurrence (P<0.05)." (PMID 39963406, 2025). "Circulating miRNA signatures, including single- and multimarker panels, demonstrate diagnostic AUCs up to 0.99 for early-stage HCC and distinguish HCC from cirrhosis more accurately than alpha-fetoprotein." (PMID 41007803, 2025). "More importantly, miR-200a-3p combined with AFP showed effective predictive performance in the differential diagnosis between CHB/cirrhosis and HCC (AUC > 0.9) in the discovery and testing cohorts." (PMID 41459517, 2025). "Annual MRI is advised from diagnosis, with earlier imaging if ultrasound findings, AFP elevation, or cirrhosis are present." (PMID 40684071, 2025).
Cirrhosis (continued). "Both circ_0009910 and circ_0027478 significantly and positively correlated with tumor size, AFP levels, and disease severity, including advanced tumor stage, metastasis, and cirrhosis, highlighting their potential as biomarkers for HCC progression." (PMID 40429981, 2025). "GAAD and GALAD demonstrated consistently higher sensitivity than ultrasound plus AFP across subgroups by age, sex, cirrhosis etiology, and Child Pugh class." (PMID 41375033, 2025). "Univariate analysis revealed that cirrhosis (p = 0.009), serum AFP (p = 0.011), tumor size (p = 0.001), CLIP score (p < 0.001), AJCC stage (p < 0.001), and high SERPING1 levels (p = 0.011) were significant predictors of improved overall survival." (PMID 39474998, 2025). "In brief, factors such as failure to achieve SVR, cirrhosis, reduced albumin levels, elevated alpha-fetoprotein (AFP), low platelet count, and the presence of indeterminate liver nodules before starting DAA therapy are associated with an increased risk of HCC." (PMID 41374406, 2025). "HCC patients showed significantly higher TB, DB, and AFP levels than those cirrhosis and control groups, whereas ALB and Total Protein exhibited significantly reduced levels." (PMID 39753619, 2025). "These include male gender, age, obesity, years with cirrhosis, family history of liver cancer, baseline alpha-fetoprotein (AFP), albumin, and AST." (PMID 39982238, 2025). "The experimental and control groups were comparable in terms of age, sex, HBV status, cirrhosis history, alanine aminotransferase, AFP positivity, and SAA/CRP levels." (PMID 40660552, 2025). "These include, in particular, the presence of cirrhosis, evidence of portal hypertension, high AFP level at the start and end of DAA therapy." (PMID 38273255, 2024). "We found that the aMAP score was an independent risk factor for HCC development after adjusting for HBeAg status, AFP level, and the presence of cirrhosis." (PMID 39001216, 2024). "Core-fucosylated serum IgG was significantly increased in HBV-HCC compared to HBV-related cirrhosis, HBV carriers and healthy subjects, and have general diagnostic performance than AFP in the training set and validation cohorts." (PMID 38561745, 2024). "Decreased expression of TH in HCC patients shown positive association with survival and negatively correlated with tumor size, tumor number, AFP level and cirrhosis." (PMID 38610044, 2024). "Clinicopathological data were obtained including the size, grade and stage of tumors, vascular invasion status, alpha-fetoprotein levels, and cirrhosis status." (PMID 38929532, 2024). "For intermediate-risk patients, US + AFP and AMRI were optimal for female patients depending on the patient type (e.g., AMRI preferred for obese patients with Child-Pugh A cirrhosis), and GALAD was optimal for male patients." (PMID 39234558, 2024). "The results we obtained indicated that serum AFP, tumor size, cirrhosis, tumor number and SNRNP70 NOD were valuable prognostic indicators for OS and TTR." (PMID 38500533, 2024). "For patients with cirrhosis at high risk of developing HCC, screening with an ultrasound of the liver and serum alpha fetoprotein (AFP) is recommended every 6 months." (PMID 39594783, 2024). "Based on this evidence, we, the authors, recommend that all patients with compensated HCV cirrhosis who achieve SVR post-DAA therapy undergo semiannual AFP testing and US indefinitely." (PMID 39319076, 2024). "Further studies will be conducted to update the aMAP score by incorporating other significant factors, including AFP levels and cirrhosis status, and to validate it externally across multiple centers." (PMID 39001216, 2024). "The APGA model utilizes AST, platelet count, GGT, and AFP to predict both severe fibrosis and cirrhosis." (PMID 38472929, 2024).
Cirrhosis (continued). "Multivariable analysis confirmed that the aMAP score, particularly in the high-risk group, was an independent predictor of HCC development after adjusting for AFP level, presence of cirrhosis, and HBeAg status." (PMID 39001216, 2024). "Cirrhosis, tumor invasiveness, blood AFP levels, HBV status, metastatic disease, HCC stage, and survival are all attributes encompassed within this classification." (PMID 38799446, 2024). "The increase was closely related with patients’ presence of cirrhosis and vascular invasion, higher AFP, and advanced Edmondson grade and TNM stage." (PMID 39412398, 2024). "Patients with HCC were older (69 vs. 61 years, p = 0.013) and had a higher cirrhosis incidence (81.0 vs. 28.9%, p < 0.001), higher AFP (6.0 vs. 3.3, p = 0.003) and higher APRI (0.8 vs. 0.5, p = 0.005)." (PMID 39064561, 2024). "DNV group had significantly lower level of alpha-fetoprotein (AFP), lower rates of decompensated cirrhosis ( P < 0.05)." (PMID 38355447, 2024). "The collected data include patients’ names, gender, age, history of chronic hepatitis, degree of cirrhosis, levels of AFP and total bilirubin, tumor size, staging, and differentiation level." (PMID 39766793, 2024). "We also explored other predictors, such as AFP level, cirrhosis status, and treatment received, alongside the aMAP score." (PMID 39001216, 2024). "For HCC diagnosis, the AUC values were 0.992 and 0.822 for the Normal and Cirrhosis groups, respectively, surpassing those of AFP, CA19-9, CEA, and CA12-5." (PMID 38890166, 2024). "Our patients have similar clinical features resembling previously reported patients, including low-GGT cholestasis, rapidly progressive liver failure/decompensated cirrhosis, vitamin K independent coagulopathy, and markedly elevated AFP levels." (PMID 38641832, 2024). "In one case–control study, which included 164 HCC patients and 324 controls, LC-SPIK had an AUC of 0.87 compared to only 0.70 for AFP in distinguishing HCC from liver disease controls (cirrhosis, HBV/HCV)." (PMID 38611638, 2024). "Compared to those without HCC, these patients were older (>65 years), more likely to have cirrhosis, and exhibited higher AFP levels and liver fibrosis scores." (PMID 39064561, 2024). "Increased POLR2J4 showed a significant relationship with the severity of patients’ conditions, such as the presence of cirrhosis and vascular invasion, increased AFP, advanced Edmondson grade, and TNM stage." (PMID 39412398, 2024). "The presence of cirrhosis, the clinical stage (CLIP and BCLC), pathological stage, tumor size, and alpha-fetoprotein were significantly associated with a worse outcome." (PMID 38107324, 2023). "First, we compared patients with cirrhosis (n=158) to patients with HCC with AFP levels below 20 ng/mL (n=76) and those with early-stage HCC (n=60)." (PMID 37708457, 2023). "The HCC group had significantly higher levels of total bilirubin, aspartate aminotransferase, alanine aminotransferase, alkaline phosphatase, and AFP but a lower level of albumin than the cirrhosis and healthy groups." (PMID 36673067, 2023). "These patients displayed a significantly higher proportion of both advanced fibrosis and cirrhosis compared to those with normal serum AFP levels (0–7 ng/mL)." (PMID 37241155, 2023). "Nevertheless, a meta-analysis conducted in 2018 and including 13,367 patients showed that the sensitivity of US for the detection of small HCC in cirrhosis was significantly higher when AFP was added to the US (45% vs. 63%, respectively)." (PMID 36831120, 2023). "For predicting advanced fibrosis and cirrhosis, serum AFP had a significantly higher AUROC compared to APRI and FIB-4." (PMID 37241155, 2023). "Diabetes, cirrhosis, CP class A5/6, AFP ≥200, tumor size ≥10 cm, and initial treatment were significantly associated with mortality in univariate analysis." (PMID 36625289, 2023).